STK33 (serine/threonine kinase 33)
Diseases named in the same sentence as STK33 in open-access papers (continued):
Sharing a sentence is not in itself a finding about the gene and the disease.
tumor (continued). "Abrogation of STK33 correlated with a significant decrease of tumor size when compared to control tumors." (PMID 29100402, 2017). "Next, we interrogated the potential involvement of STK33 in HIF-1α regulation by HSP90 in hypoxic tumor cells." (PMID 29100402, 2017). "Of note, STK33 involves in the “synthetic lethal” process of a variety of tumor cells, which depends on the Ras oncogene." (PMID 25603720, 2015). "Similarly, STK33 silencing strongly reduced the Bufalin‐induced cleaved‐PARP1 expression, and results of the colony formation assays confirmed that the tumor cells became less sensitive to Bufalin following STK33 knockdown." (PMID 40908551, 2025). "Moreover, our previous findings indicated that STK33 participates to the tumor growth promoted by the chaperone." (PMID 29100402, 2017). "Since VEGF-A is secreted by tumor cells through the activation of HIF-1α we reasoned that STK33 might affect VEGF levels." (PMID 29100402, 2017). "However, the exact molecular mechanism of how STK33 is involved in tumor progression remained elusive to date." (PMID 29100402, 2017). "Given that HSP90 inhibition impairs tumor growth in an STK33-dependent manner we sought to investigate whether STK33 does also participate in de novo tumor vascularization promoted by the chaperone." (PMID 29100402, 2017). "However, these few data published relevant to STK33 expression in different types of tumor are conflicting and the possible role of STK33 on human HSCC has not been investigated to date." (PMID 25603720, 2015). "Previous studies on human somatic tumors have shown that STK33 acts as a novel tumor gene." (PMID 25603720, 2015). "The expression of STK33 in human normal and hypopharynx tumor tissue was examined by IHC." (PMID 25603720, 2015). "Our in vivo data imply that STK33 might play an important role in tumor-driven vascularization." (PMID 29100402, 2017). "Mechanistically, STK33 phosphorylates and increases the CCAR1 stability, thereby stimulating tumor progression." (PMID 40908551, 2025). "In tumor-related diseases, STK33 has been shown to suppress mitochondrial apoptosis by inhibiting BAD activity, enhancing tumor cell survival and proliferation." (PMID 40978038, 2025). "Mechanistically, STK33 phosphorylates and stabilizes CCAR1, which promotes tumor growth and metastasis, thereby driving tumor progression." (PMID 40908551, 2025). "Previous in vitro and in vivo studies have demonstrated that overexpression of STK33 promotes the malignant biological behaviors of pancreatic ductal adenocarcinoma (PDAC) cells, while its inhibition suppresses tumor cell malignancy." (PMID 38413579, 2024). "Patients with hypomethylation of PAX9, STK33, GPR150, INSM1, and EPHX3 showed a shorter survival time and a higher tumor‐related mortality." (PMID 31131446, 2019). "Altogether, our findings indicate that STK33 interferes with signals from hypoxia and HSP90 to promote tumor angiogenesis and tumor growth." (PMID 29100402, 2017). "Serine/Threonine kinase 33 (STK33) serves as an oncogene as it has been found involved in pathways regulating cell proliferation, differentiation, tissue invasion, metastasis, and tumour development." (PMID 37277696, 2023). "Firstly, we found that endogenous STK33 interacted with hypoxia-stabilized HIF-1α; secondly, deletion of STK33 in tumor cells subjected to low oxygen atmosphere resulted in a reduced HIF-1α accumulation which thirdly, was associated with impaired hypoxia-induced HIF-1α promoter activity." (PMID 29100402, 2017). "This indicates that STK33 over-expression may play a crucial role in the pathogenesis of HSCC, which is consistent with the findings in other types of tumor." (PMID 25603720, 2015).
tumor (continued). "In addition, it raises the hypothesis of potential cooperation between STK33 and other HSP90 client kinase proteins in order to ensure a robust and lasting molecular signaling response during tumor development." (PMID 29100402, 2017). "Furthermore, it 3) raises the hypothesis of potential cooperation between various HSP90 client kinase proteins such as STK33 and PKD2, for a more robust and lasting effect during tumor development." (PMID 29100402, 2017).
psychiatric disorder (1 paper, 2019). A disorder characterized by behavioral and/or psychological abnormalities, often accompanied by physical symptoms. "To date, STK33 has not been associated with any psychiatric disorder." (PMID 31578828, 2019).
STK33 also shares sentences with these, for which no sentence is quoted: depression (2 papers); glioblastoma (2); hepatocellular carcinoma (2); Hypertension (2); schizophrenia (2); acute myocardial infarction (1); alcohol dependence (1); colorectal tumor (1); infection (1); large cell lung cancer (1); lung adenocarcinoma (1); neuroblastoma (1); neurological disorders (1); oligoasthenoteratozoospermia (1); pancreatic ductal adenocarcinoma (1); rheumatoid arthritis (1); Sepsis (1); triple-negative breast carcinoma (1).